LINC01387 (long independently transcribed non-coding RNA 1387)
Synonyms: C18orf64
Gene: Long non-coding RNA gene on chromosome 18 (6,413,730 to 6,590,653, forward strand). Ensembl gene ENSG00000265944.
Diseases named in the same sentence as LINC01387 in open-access papers:
LINC01387 is named in the same sentence as 1 disease in open-access papers, as found by Europe PMC text mining. Sharing a sentence is not in itself a finding about the gene and the disease.
LINC01387 shares sentences with these, for which no sentence is quoted: cancer (1 paper).